TYK2 (tyrosine kinase 2)
Diseases named in the same sentence as TYK2 in open-access papers (continued):
Sharing a sentence is not in itself a finding about the gene and the disease.
tumor (continued). "The tumor data in host mice with deletion of Tyk2 in specific immune subsets showed that TYK2 signaling in T cells, NK cells, macrophages, neutrophils or Kupffer cells is not required for immunosurveillance of CRLM." (PMID 40991399, 2026). "We characterized tumor parameters and immunophenotypes of liver metastases in TYK2-/- and TYK2Δhem host mice four weeks after intrasplenic injection of AKP organoids." (PMID 40991399, 2026). "Analysis of single-cell RNA sequencing data from primary CRC and CRLM revealed that TYK2 was predominantly expressed in a dendritic cell population destined to present antigens in tumor-draining lymph nodes." (PMID 40991399, 2026). "IVIS data showed a strongly increased tumor burden in TYK2-/- host mice compared to littermate control host mice (TYK2+/+) three weeks post injection, which was confirmed by macroscopic inspection of livers four weeks post injection." (PMID 40991399, 2026). "In contrast to cancer cell-intrinsic functions, the role of TYK2 in the tumor immune microenvironment is much better defined." (PMID 40991399, 2026). "The relative percentage of GFP-expressing metastatic tumor tissue and GFP-negative stroma was similar in TYK2-proficient and TYK2-deficient host mice despite the significant difference in tumor burden." (PMID 40991399, 2026). "In one study, CLDN6 was expressed at low levels in a CRC cell line (SW1116); when CLDN6 was experimentally overexpressed, it suppressed the cells’ migratory and invasive abilities, apparently by activating the tumor-suppressive TYK2/STAT3 pathway." (PMID 40687428, 2025). "Despite its engagement at various cytokine receptor complexes, the predominant impact of TYK2 in the investigated immune cells under homeostatic conditions and upon tumor infiltration is on IFN responses." (PMID 40025196, 2025). "To the best of our knowledge, we also provide the first detailed RNA signatures of kinase-inactive TYK2 in innate and adaptive splenic and tumor-derived immune cells." (PMID 40025196, 2025). "We used the MC38 adenocarcinoma transplantable tumor model previously established in Tyk2−/− mice since it allows simple separation of tumor-infiltrating CD45+ hematopoietic cells from tumor cells." (PMID 40025196, 2025). "The major impact of loss of TYK2 protein or kinase activity in splenic homeostatic macrophages, NK and CD8+ T cells and tumor-derived cytolytic cells is on IFN responses." (PMID 40025196, 2025). "We found that in splenic homeostatic and tumor-derived immune cells kinase-active TYK2 mainly impacts on the IFN response gene signature." (PMID 40025196, 2025). "We have identified a crucial role of TYK2 in NK and T cell-mediated tumor cell elimination and in shaping the tumor microenvironment in various cancer models." (PMID 40025196, 2025). "Our study unravels the transcriptional impact of TYK2 in naïve immune cells and upon exposure to a tumor microenvironment." (PMID 40025196, 2025). "The total number of significantly downregulated DEG in Tyk2−/− and Tyk2K923E NK cells was approximately twofold higher than in tumor-infiltrating CD8+ T cells." (PMID 40025196, 2025). "Here we relate the transcriptome changes to phenotypical changes observed in TYK2-deficient (Tyk2−/−) and TYK2 kinase-inactive (Tyk2K923E) mice in naïve splenic immune cells and upon ex vivo IFN treatment or in vivo tumor transplant infiltration." (PMID 40025196, 2025). "Tumor budding (Bd) was negatively correlated with the percentage of strong pixels for TYK2 (ρ = −0.270, p = 0.0096)." (PMID 39518103, 2024). "The effects of TYK2 on tumor growth and metastasis in HNSCC were finally determined by cell function assays." (PMID 36531252, 2022). "Our data indicate additive tumor-suppressive functions of Tyk2 in epithelial cancer cells and stromal cells." (PMID 36185806, 2022).
tumor (continued). "The results demonstrated that the expression of TYK2 mRNA was upregulated in the 25 HNSCC tissues compared to the adjacent non-tumor tissues, and were consistent with the data retrieved from the TCGA datasets." (PMID 36531252, 2022). "Our analysis of gene expression profiles in the tumour microenvironment identified genes implicated in inflammation or immune response, such as PTGS2 and TYK2." (PMID 36077723, 2022). "Our data revealed tumor-suppressive functions of Tyk2 in cancer cells as well as immune cells of the tumor microenvironment." (PMID 36185806, 2022). "Tyk2 deletion in cancer cells or in immune cells increased the tumor burden, but only combined deletion in both cellular compartments promoted tumor progression." (PMID 36185806, 2022). "All Tyk2-deficient mouse models showed a higher tumor burden after AOM-DSS treatment compared to their corresponding wild-type controls (Tyk2+/+ and Tyk2fl/fl), demonstrating tumor-suppressive functions of Tyk2 in immune cells and epithelial cancer cells." (PMID 36185806, 2022). "A total of 30 IL22RA1-correlated genes (e.g. IL17D, IL22RA2, IL20RB, IL10RA, IL10RB, TSLP and TYK2) are involved in the JAK/STAT pathway which promotes tumor progression." (PMID 35874683, 2022). "Subsequent genetic knockdown of TYK2 in MPNST cell lines resulted in decreased tumor growth and increased cell death." (PMID 34439323, 2021). "The tissue array results showed that TYK2 protein levels were positively correlated with the tumor clinical stage while it was negatively correlated with patient survival rate in ESCC." (PMID 33731185, 2021). "In tumor B cell lines, Fyn interacts with the activated forms of TYK2 and JAK2 in response to IFN-α or IFN-γ stimulation respectively." (PMID 33668421, 2021). "Taken together, these finding indicated that cirsiliol inhibited ESCC tumor growth in vivo by targeting TYK2." (PMID 33731185, 2021). "Herein, we investigated the role of TYK2 in ESCC and found that the mRNA and protein levels of TYK2 were expressed highly in the most tumor tissues." (PMID 33731185, 2021). "In follow-up studies employing a metastatic mouse xenograft model with left ventricle tumor injection, shRNA knockdown of Tyk2 decreased MPNST tumor burden and increased overall survival." (PMID 34439323, 2021). "In this study, we found that the expression levels of JAK3 and TYK2 were higher in tumor tissues than in normal tissues in STAD." (PMID 33083484, 2020). "This will enable us to define the molecular/functional intersection of TYK2 as a tumor surveyor and/or as a promoter of carcinogenesis by shaping immune and oncogenic pathways." (PMID 31936322, 2020). "The data from mouse models indicate that the functions of TYK2 in tumor surveillance are context-dependent." (PMID 31936322, 2020). "TYK2 has a kinase-independent function in NK cell-mediated tumor surveillance, as evidenced by the partial restoration of NK-cell maturation and cytotoxicity in Tyk2K923E mice." (PMID 31936322, 2020). "For further details on the role of TYK2 in tumor-cell invasiveness, we refer the reader to a recent review." (PMID 31936322, 2020). "The pleiotropic and context-dependent activities of these cytokines show that TYK2 is responsible for tipping the balance between tumor-restrictive and tumor-promoting functions." (PMID 31936322, 2020). "Previous studies have also clarified the significant role of JAK3 and TYK2 in the tumor microenvironment and immune response." (PMID 33083484, 2020). "Studies of TYK2 in anticancer immunity in mice have revealed a pivotal role of TYK2 in the NK- and T-cell-mediated elimination of tumor cells." (PMID 31936322, 2020). "To this end, we first investigated both IL10RA and IL10RB and its downstream targets JAK1 and TYK2 gene expression levels in 370 HCC tumor samples using the publicly available The Cancer Genome Atlas (TCGA) dataset." (PMID 32443546, 2020).
tumor (continued). "For the role of TYK2 in tumor immune-surveillance we refer to the recent Special Issue of Cancers “JAK-STAT Signaling Pathway in Cancer”." (PMID 31694222, 2019). "HSP90 inhibitor treatments in various tumor settings showed beneficial effects by reducing the activity of TYK2 or its fusion proteins." (PMID 31694222, 2019). "On a molecular mechanistic level, the cell intrinsic tumor-promoting consequences of low TYK2 or LOF of TYK2 currently remain elusive." (PMID 31694222, 2019). "The highest TYK2 expression level was found in a tumor with a previously reported NFkB-TYK2 fusion protein." (PMID 30131584, 2019). "IFNs in general are capable of promoting apoptosis of cancer cells; hence, provided that IFN stimulus and responsiveness in the tumor is given, TYK2 acts tumor suppressive." (PMID 31694222, 2019). "In vitro studies showed that in hematopoietic tumor cells the PTP SHP1 suppresses growth via accelerating the TYK2 protein degradation." (PMID 31694222, 2019). "Deletion of Tyk2 was confirmed by PCR of the Tyk2 gene locus, western blot of tumor tissue and real-time RT-PCR." (PMID 30131584, 2019). "Using mice with NKp46+ cell-specific deletion of Tyk2 revealed that the impact of TYK2 on NK cell maturation and tumor surveillance is cell-extrinsic and depends on the presence of TYK2 in dendritic cells." (PMID 31781102, 2019). "Third, we demonstrate that reduced levels of Tyk2 leads to decreased tumor growth in subcutaneous and left ventricular models of tumor inoculation in a murine MPNST." (PMID 31278855, 2019). "Knockdown of IL-10RA in ALCL cell lines resulted in growth arrest, implicating aberrantly expressed IL-10 and IL-22 in autocrine loops that provided a mechanism for aberrant TYK2 activation in tumor cells." (PMID 30131584, 2019). "The decreased cytotoxic activities of NK and NKT cells in TYK2-/- mice are considered to be involved in virus-induced tumor development." (PMID 29725107, 2018). "We suppose that in both healthy and tumor contexts, this effect depends on the impaired phosphorylation of molecules involved in the IL-22 proximal signaling, such as IL-22R1 and Tyk2." (PMID 28445952, 2017). "Several studies have demonstrated that TYK2 has essential functions in tumor immunosurveillance." (PMID 40991399, 2026). "Rather, there was lower GFP expression in tumor cells of TYK2-deficient host mice although the reduction was non-significant." (PMID 40991399, 2026). "We hypothesized that the increased metastatic burden in TYK2-/- host mice is due to a defect in immune functions leading to impaired tumor immunosurveillance." (PMID 40991399, 2026). "Due to the lack of specific antibodies for TYK2 immunohistochemistry and the scarcity of Tyk2 mRNA reads in single cell sequencing data, it remains to be demonstrated whether TYK2 expression is increased in cancer cells or cells of the tumor microenvironment." (PMID 40991399, 2026). "It is possible that TYK2 upregulation in human tumor cells is oncogenic, which could explain this result." (PMID 40991399, 2026). "We previously established the requirement for TYK2 in various tumor surveillance settings." (PMID 40025196, 2025). "A previous study reported that TYK2 had a role in CTL-mediated tumor surveillance." (PMID 38351043, 2024). "Meanwhile, suppression Tyk2 cascade was shown to interrupt such oncogenic signaling cascades, which could potentially contribute to its anti-tumor effects in preclinical cancer models." (PMID 39564119, 2024). "The findings confirmed that TYK2 might play an active role in tumor immune surveillance and defense in HNSCC." (PMID 36531252, 2022). "The findings demonstrated that TYK2 could serve as a suppressor of tumor growth and holds significant promise as a novel biomarker for assessing the prognosis of patients with HNSCC and aid in immunotherapy against HNSCC." (PMID 36531252, 2022). "In conclusion, we have identified a tumor-suppressive function of Tyk2 in stromal and CRC cells." (PMID 36185806, 2022).
tumor (continued). "HSPB1, EGFR, and TYK2 were highly expressed in tumor tissue in the Human Protein Atlas database." (PMID 36171217, 2022). "However, specific deletion of Tyk2 in hematopoietic cells or in intestinal epithelial cells was insufficient to accelerate tumor progression, while deletion in both compartments promoted carcinoma formation." (PMID 36185806, 2022). "In addition, NK cell-specific deletion of TYK2 decreases anti-bacterial responses while leaving NK cell-mediated tumor surveillance intact in contrast to global TYK2 knockout mice." (PMID 34073410, 2021). "Additionally, genetic knockdown of Tyk2 in murine MPNST cells resulted in decreased tumor burden in subcutaneous tumors and metastatic tumor models." (PMID 34439323, 2021). "In addition, TYK2 plays an important role in tumor immunosurveillance as well as inflammatory cytokine signaling in cancer development and metastases, which was recently reviewed." (PMID 34439323, 2021). "Furthermore, the tumor growth of Cell-derived xenograft (CDX) mice model was reduced after TYK2 knockdown and the average of tumor weight in the TYK2 knockdown group was lower than the control group in the CDX mice model." (PMID 33731185, 2021). "Work in a murine model of breast cancer has shown that TYK2 deficiency enhances tumor growth and metastasis by stimulating MDSCs rather than by inhibiting the activity of T cells or NK cells." (PMID 31936322, 2020). "In summary, we provide evidence of naturally occurring catalytic loss-of-function TYK2 variants and reduced expression of TYK2 in B-ALL patients and propose that both mechanisms could contribute to facilitate tumour expansion." (PMID 33260630, 2020). "TYK2 may drive beneficial or detrimental activities, which we explain based on the concepts of tumor immunoediting and the cancer-immunity cycle in the tumor microenvironment." (PMID 31936322, 2020). "The biology and biochemistry of JAKs, TYK2-dependent cytokines and cytokine signaling in tumor surveillance are well covered in recent reviews and the oncogenic properties of TYK2 are reviewed in the recent Special Issue ‘Targeting STAT3 and STAT5 in Cancer’ of Cancers." (PMID 31936322, 2020). "In addition, without providing molecular insights, a siRNA screen assessing the role of the tyrosine kinome in metastasis formation identified TYK2 as a promoter of invadopodia, which are cellular structures characteristic for tumor cell migration." (PMID 31694222, 2019). "The underlying reason for these conflicting reports may be attributed to the anti-proliferative/pro-apoptotic and/or tumor surveillance properties of TYK2, as well as the undetermined tumor cell intrinsic and extrinsic state of TYK2." (PMID 31694222, 2019). "Furthermore, in a left ventricular tumor injection model of tumor dissemination and metastasis, we observed decreased tumor burden over time in mice injected with Tyk2‐deficent cells compared to mice injected with control cells." (PMID 31278855, 2019). "Hence, targeting TYK2 may serve as a therapeutic intervention for neoplasms harboring the NPM::TYK2 rearrangement." (PMID 37810974, 2023). "Overexpression of CLDN9 could promote tumor cell invasion through Tyk2/STAT3 signaling." (PMID 35223866, 2021). "After TYK2 activation, transcription factors such as signal transducer and activator of transcription 1 (STAT1) and STAT3, are dimerized and activated, thereby promoting the transcription of related genes and causing abnormal tumor cell proliferation and differentiation." (PMID 33731185, 2021). "Finally, we summarize current knowledge of TYK2 functions in mouse models of tumor surveillance." (PMID 31936322, 2020).
tumor (continued). "Hence, our data show that ALCL is a tumor that is dependent on TYK2 for cell survival, that TYK2 is activated through an autocrine loop involving IL-10 and IL-22, and that TYK2 promotes cell survival at least in part through activating the expression of the BCL2 family protein, MCL1." (PMID 30131584, 2019). "In summary, these data demonstrate that TYK2 is predominantly expressed in human LAMP3+ CCR7+ cDCs that are enriched in CRLM and predicted to activate T cells in tumor-draining lymph nodes." (PMID 40991399, 2026). "Here we investigate in detail the impact of TYK2 on common or cell-type-specific gene expression of macrophages, NK and CD8+ T cells under steady state, IFN-treated and tumor-derived conditions." (PMID 40025196, 2025). "A kinase-independent function of TYK2 was found in NK cells, in which kinase-inactive TYK2 (TYK2K923E) restored in part NK cell maturation and cytotoxicity against tumor cells in vitro and in vivo." (PMID 40025196, 2025). "WT and Tyk2-mutant immune cell transcriptomes were also compared under IFN-treated and tumor-derived conditions." (PMID 40025196, 2025). "The expression levels of TYK2 mRNA in pan-cancer tissues were analyzed using the TIMER2 database, and the differential expression of TYK2 between the normal and tumor tissues was explored." (PMID 36531252, 2022). "Our study shows that Tyk2 prevents Ido1 expression in CRC cells and promotes CRC immune surveillance in the tumor stroma." (PMID 36185806, 2022). "TYK2 is essential for the cytotoxic functions of CD8+ T cells and natural killer (NK) cells, and promotes the maturation, cytotoxicity, and anti-tumor activity of NK cells in the host environment." (PMID 36531252, 2022). "The results demonstrated that the expression of TYK2 mRNA was significantly upregulated in multiple cancers, including HNSCC, compared to that of normal matched non-tumor tissues." (PMID 36531252, 2022). "In order to assess the anti-tumor activity of cirsiliol in vivo, LEG73 and LEG104 cases with high level of TYK2 were selected from the ESCC PDX specimen repository to develop the PDX mouse model." (PMID 33731185, 2021). "In B-cell lymphoma cells, binding of the CD86 ligand to cytotoxic T-lymphocyte-associated antigen 4 (CTLA4) results in recruitment and phosphorylation of TYK2, which activates STAT3 to drive transcription of genes promoting tumor growth and survival." (PMID 34439323, 2021). "Recent reports investigated the pro-survival mechanisms of TYK2 signaling using pharmacologic or genetic inhibition of TYK2 or STAT3 in various cancer cell lines and mouse tumor models." (PMID 34439323, 2021). "The microarray analysis showed that Tyk2, Jack1, Jack2 and their phosphorylated forms are activated by IFN-τ in tumor cells." (PMID 32626522, 2020). "JAK3/TYK2 levels were significantly increased in STAD during subgroup analyses based on gender, tumor grade, cancer stages, and nodal metastasis status." (PMID 33083484, 2020). "Mechanistically, it was established that CD86-CTLA4 engagement resulted in recruitment/activation of TYK2, which, in turn, led to a STAT3-driven tumor-promoting transcriptional program." (PMID 31694222, 2019). "We furthermore show that TYK2 is activated by an autocrine loop involving IL-10 and IL-22 and that STAT1 and STAT3 are essential mediators of aberrant tumor cell survival through activation of the pro-survival protein MCL1." (PMID 30131584, 2019). "The JAK/TYK2-STAT-IRF signalling pathway is involved in many processes including immunity, cell division, cell death and tumor formation." (PMID 31861316, 2019). "The TYK2–pYSTAT1 pathway positively regulates MCL1 expression in ALCL cells, contributing to this aberrant tumor cell survival." (PMID 30131584, 2019). "Silencing JAK1, JAK2 or TYK2 using RNA interference (RNAi) inhibits FGF2-mediated proliferation and results in the sensitization of tumor cells to chemotherapy-induced killing." (PMID 21625473, 2011).